CRH (corticotropin releasing hormone)
Diseases named in the same sentence as CRH in open-access papers (continued):
Sharing a sentence is not in itself a finding about the gene and the disease.
Anxiety (continued). "We have previously reported that ACE2 overexpression restricted to CRH synthesizing cells leads to suppression of CRH synthesis, blunting of HPA axis activation and attenuation of anxiety-like behavior." (PMID 37638323, 2023). "Increased corticotropin releasing hormone (CRH) gene expression and circulating corticosterone (CORT) levels in GF mice are correlated with depression and anxiety-like behaviors." (PMID 35744601, 2022). "There is increasing evidence that CRH neurons of the PVN are central players not only in appetite regulation but also in linking stress and anxiety behavior." (PMID 36271504, 2022). "We further determined measures of aversion-related signaling (kappa opioid receptor, dynorphin, and corticotropin releasing hormone mRNA expression) in the basolateral amygdala (BLA), a brain region well characterized for its role in anxiety and aversion." (PMID 36648898, 2022). "Our correlation analyses further supported that anxiety (in MBT) and depression levels (in TST) are inversely correlated with FOSB positivity in ovBNST/CRH cells, in agreement with previous findings in rats." (PMID 36213293, 2022). "Animal studies on the effects of spexin in anxiety and depression indicate a connection between SPX and the CRH system, while the CRH system has an established connection to the serotonergic system." (PMID 36004833, 2022). "The ovBNST and CeA CRH activity was inversely, while the cpEW/UCN1 and DR/5-HT directly correlated with MBT anxiety and TST depression levels suggesting their opposing contribution to the control of mood status (for review see: 19)." (PMID 36213293, 2022). "While CRH-mediated activation of CRHR1 increasesbasal and stress-induced anxiety in many brain areas, includingBLA, BNST, and PAG, a more complex picture is observedfor other brain regions." (PMID 34901719, 2021). "In contrast to CRHR1, the role of CRHR2 activation inthe manifestation of anxiety and depression is less clear, andthere are two theories trying to explain the CRHR2 involvement in the CRH behavioral effects." (PMID 34901719, 2021). "Studies have demonstrated that the levels of corticotropin-releasing hormone (CRH), which is released when anxiety stimulates the HPA axis, are significantly higher in women who have delivered a preterm infant than in those who gave birth at term." (PMID 34646839, 2021). "The increase of exogenous ACE2 inhibited the synthesis of CRH, while the decrease of CRH synthesis changed the central management of psychological stress, thus weakening the activation of HPA axis and alleviating anxiety-like behavior." (PMID 34531719, 2021). "An important source of CRH in the BST comes from CRH projections from the CEA to the dorsolateral BST (BSTdl), and those projections are necessary for the induction of stress-induced anxiety." (PMID 33867924, 2021). "Given the massive impact of anxiety, mood, and substance use disorders on our society, further research into BST CRH signaling is critical to alleviate the social and economic burdens of those disorders." (PMID 33867924, 2021). "Activation of the amygdala CRH system promotes anxiety and fear and activates the PVN CRH and the LC-NE systems." (PMID 34177605, 2021). "EA significantly reduced the expression of CRH and CRHR1 mRNA in the paraventricular nucleus of the hypothalamus in a rat model of stress-induced anxiety." (PMID 34306138, 2021). "The amygdala has been shown to play a critical role in the physiopathology of anxiety and it is critically involved in the regulation of the HPA axis, more specifically, through CRH projections from the CeA, which stimulate the hypothalamic PVN." (PMID 32499732, 2020). "In contrast, decreased CRH and/or GR expression levels as well as Dex suppression being overridden (denoting impaired negative central feedback) has been associated with chronic stress (not burn-out) and major or atypical depression, where anxiety does not necessarily play a major role." (PMID 32298279, 2020).
Anxiety (continued). "Activation of the HPA axis occurs through the corticotropin releasing hormone (CRH), which binds to CRH1 and CRH2 receptors, whose activation regulate several behavioral and physiological processes including anxiety and sleep." (PMID 32116534, 2020). "Some of these, at least in part, have been attributed to the potential effect of anti-anxiety agents on transcriptional regulation of different molecules involved in the regulation of the HPA axis, including GRs, MRs, and CRH." (PMID 32499732, 2020). "We recently demonstrated that a specific subpopulation of VTA-projecting, GABAergic CRH neurons in the extended amygdala (CeA and BNST) act anxiety-suppressing by positively modulating dopamine release under physiological conditions." (PMID 31619956, 2019). "Although the scale is simply based on a self-evaluation scale, our results indicated the potential finding that anxiety across psychiatric disorders, including depression, is represented by a biological scale, such as DEX/CRH." (PMID 27582123, 2016). "Behaviorally, the hypothalamic neuropeptide corticotrophin-releasing hormone (CRH), a major driver of the HPA axis, induces anxiety, while CRH receptor-1 antagonists or genetic ablation of the receptor reduce anxiety." (PMID 25756305, 2015). "Anxiety- and depressive-like behaviors in animal models can be manifested as a result of manipulating the HPA axis and increasing circulating levels of CRH." (PMID 25162235, 2014). "Nevertheless, here we demonstrate the programming effect of neonatal LPS challenge on other components of the CRH system, which play an unequivocal role in regulation of the ANS, HPA axis activity and anxiety-like behaviours." (PMID 23483921, 2013). "A similar mouse model overexpressing forebrain CRH transiently from 8 to 11 weeks of age, shows increased cortex and hippocampal CRH and increased basal CORT levels with a trend towards mild anxiety in the LD test and active coping in the FST." (PMID 23077729, 2012). "This dysfunction is believed to be due in part to hyperactive CRH neurons, which leads to overactivity of the HPA axis and produces symptoms of anxiety and depression." (PMID 22738088, 2011). "EtOH exposure in male rats increases corticotropin-releasing hormone (CRH) mRNA in the paraventricular nucleus of the hypothalamus (PVN), a brain region responsible for coordinating stress and anxiety responses." (PMID 22039522, 2011). "Similarly, CRHR1, the receptor for corticotropin-releasing hormone, is a key component of the hypothalamic–pituitary–adrenal (HPA) axis and plays a vital role in managing anxiety and stress responses." (PMID 40243462, 2025). "Considering the associations between CRH and anxiety, future studies could explore the interaction between central CRH circuits and TRN in individuals with varying levels of trait anxiety or in animal models of stress-induced anxiety." (PMID 40830097, 2025). "In contrast, chronic or excessive CRH exposure (as seen in toxic stress or trauma) disrupts this balance, leading to maladaptive plasticity, HPA axis dysregulation, and increased vulnerability to anxiety, depression, and metabolic disease." (PMID 40864786, 2025). "Another study demonstrated an anxiogenic effect of CRH/CRHR1 when the knockdown of CRHR1 in the basolateral Amy led to decreased anxiety-like behavior, and activation of the CRHR1 signaling pathway in the basolateral Amy and BNST induced anxiety-like behavior." (PMID 39595978, 2024). "Additionally, the overexpression of ACE2 in corticotropin-releasing hormone (CRH) cells can attenuate the activation of the hypothalamic–pituitary–adrenal (HPA) axis, thereby alleviating anxiety-like behavior." (PMID 39337446, 2024). "Overall, we can conclude that the altered CRH signaling is probably not involved in the development of CKD-induced anxiety at the time when sample collection was done in our study." (PMID 37989901, 2024).
Anxiety (continued). "In this study, it was found that the WLR01 strain can reduce the secretion and release of CORT and CRH in mice, indicating that WLR01 may alleviate anxiety-like behavior and visceral hypersensitivity in WAS mice through the HPA axis." (PMID 39339809, 2024). "Increase in anxiety like behavior, increase in Bacteroidetes, decrease in Firmicutes/Bacteroidetes ratio, increase in intestinal levels of IL-6, TNF-α, 5-HT, and decrease in corticotropin-releasing hormone, BDNF, and neuropeptide Y in the brain." (PMID 37324381, 2023). "For instance, CRH, secreted from the central amygdala, binds to the basolateral amygdala CRHR1 and CRHR2 and may modulate stress-emotional memories and anxiety." (PMID 37508942, 2023). "Hence in the chronic stress disorders like PTSD, a condition of hypocortisolism, elevated CRH levels, downregulation of GABAAR with a substantial reduction in GABA levels favors hyperarousal and anxiety phenotypes of PTSD." (PMID 37097603, 2023). "The CRH/CRF gene codes for corticotropin-releasing hormone/corticotropin-releasing factor and therefore plays a pivotal role in the regulation of the HPA axis and stress responses involved in anxiety." (PMID 35998298, 2023). "Additionally, neuronal corticotropin-releasing hormone (CRH) released from the paraventricular nucleus (PVN) of hypothalamus and amygala has been shown to regulate depression and anxiety, respectively." (PMID 35873031, 2022). "Long-term noise exposure can increase the expression of corticotropin releasing-hormone (CRH) in the hippocampus and decrease the inhibition of the hypothalamic-pituitary-adrenal (HPA) axis, which may worsen depression and anxiety." (PMID 35903368, 2022). "Here, we provide first experimental evidence for a direct link between mitochondrial dysfunction in a peripheral (non-brain) tissue with anxiety-like behavior, potentially via hypothalamic CRH signaling in a GFRAL-dependent manner." (PMID 36271504, 2022). "We explored the effects of repeated restraint stress and intermittent alcohol exposure during adolescence on the mRNA expression of many genes related to the CRH and NPY systems in the amygdala because this brain region is involved in the regulation of anxiety-like behaviors." (PMID 35327395, 2022). "Since our study assessed changes in anxiety in naïve (non-stressed) mice, future studies should investigate the potential role of GH action in CRH neurons regulating anxiety after acute and chronic stress." (PMID 34576072, 2021). "Based on the plethora of preclinical evidence implicating the CRH signaling pathway in maladaptive behaviors, several clinical studies have investigated CRHR1 antagonists as potential therapeutic targets for the treatment of anxiety, PTSD, and AUDs." (PMID 33867924, 2021). "The absence of GHR in CRH cells did not affect anxiety, circadian glucocorticoid levels or restraint-stress-induced corticosterone secretion and activation of PVH neurons in both male and female mice." (PMID 34576072, 2021). "Here, the notable downregulation of CRH suggests a state not necessarily of anxiety, but of low arousal that would be consistent with the DSM criteria of ‘diminished ability to think or concentrate’28." (PMID 33589676, 2021). "There is a lot of data indicating that in the case of long-termexposure, CRH has effects that are fundamentally differentfrom acute ones (Maras, Baram, 2012), and these effects areassociated with a depressive rather than anxiety phenotype." (PMID 34901719, 2021). "Nonetheless, CRH GHR KO mice did not exhibit evidence of changes in anxiety, as compared to control mice." (PMID 34576072, 2021). "In summary, GHR ablation, specifically in CRH-expressing neurons, does not lead to major alterations in metabolism, hypothalamic–pituitary–adrenal axis, acute stress response or anxiety in mice." (PMID 34576072, 2021).
Anxiety (continued). "Some CRH-expressing, GABAergic, long-range-projecting neurons in the extended amygdala (i.e., BNST) innervate the ventral tegmental area (VTA) and may alter anxiety." (PMID 34445795, 2021). "CRH neurons in the PVH and other brain areas are key regulators of anxiety." (PMID 34576072, 2021). "It remains unclear, however, how important the effects of anti-anxiety agents on the HPA axis activity are in mediating their therapeutics benefits and moreover whether further modulation of CRH and related systems might augment our currently available agents." (PMID 32499732, 2020). "The corticotropin-releasing hormone (CRH) family consists in vertebrates of five structurally related neuropeptides that are involved in the regulation of physiological response to stress, emotional behavior, and anxiety." (PMID 32848532, 2020). "Additionally, limbic CRH and CRH receptor 1 (CRHR1) have also long been identified as central regulators of anxiety." (PMID 29904149, 2020). "Several lines of evidence suggest that those neuropeptides, which are increased by hunger (NPY and AgRP), also reduce fear and anxiety, while others released upon refeeding and in particular during states of satiety are predominantly anxiogenic (α‐MSH, CRH, and CCK)." (PMID 31271235, 2019). "Further evidence suggested that CRHRs exert their stress-modulating effects after exposure to trauma via a brain-region dependent manner, along with the findings that CRH activity in the medial prefrontal cortex (mPFC) increased stress-induced HPA activity and anxiety-related behaviors." (PMID 30898126, 2019). "However, some previous studies suggested that CRH and CORT were relatively highly secreted in the stress-induced anxiety model and irritable bowel syndrome (IBS) model with a high anxiety state." (PMID 30881446, 2019). "Therefore, more evidence is needed to define the role of CRH and CORT in inflammatory disease with anxiety symptoms." (PMID 30881446, 2019). "Corticotropin-releasing hormone (CRH) links the HPA axis to the brain's response with stress required behavior, and its activity may thus influence anxiety and stress reactions." (PMID 31866881, 2019). "Anyway, from the present study, the results indicate that regulating CRH and CORT feedback may be an important way of EA and MB to ameliorate anxiety behavior in DSS-induced colitis." (PMID 30881446, 2019). "Interestingly, our results showed that the levels of CRH and CORT were decreased significantly in the DSS-induced colitis model mice with anxiety behavior." (PMID 30881446, 2019). "Besides, several studies have suggested that CRH is a major stress-related peptide in the HPA axis, which plays an important role in the occurrence of anxiety and eliciting anxiety symptoms." (PMID 30881446, 2019). "Based on the findings from this study and previous studies, we postulate that CRH-BP may be released from SST interneurons to regulate the activity of pyramidal neurons via CRH-R1, potentially influencing anxiety-like behavior." (PMID 29066956, 2017). "The non-suppressors, as indicated by the DEX/CRH test, exhibited a high severity on the Hamilton Depression Scale and severe anxiety on the State Trait Anxiety Scale." (PMID 27582123, 2016). "Indeed, VP, co-expressed in CRH neurons in the PVN, potentiates CRH activity at the level of the pituitary corticotroph within the HPA axis, which in turn can lead to anxiety-like behaviors." (PMID 26537115, 2015). "Additionally, the central, lateral, and basal amygdala nuclei have a large population of neurons that express corticotropin-releasing hormone (CRH) and its receptors; hyperfunction of these neurons can result in increased levels of anxiety-like behaviors." (PMID 24592255, 2014). "Maternal antenatal CMD including depression and anxiety can lead to elevations of activity in the HPA axis, which increases levels of cortisol, a major stress hormone, and placental corticotropin-releasing hormone (CRH)." (PMID 24401012, 2014).
Anxiety (continued). "A similar study elevating CeA CRH levels in female rats demonstrated stress pathology changes including increased anxiety and despair-like behaviors, and impaired negative feedback of the HPA axis." (PMID 23077729, 2012). "Male Wistar rats selectively bred for high innate anxiety are characterized by elevated ACTH and corticosterone responses to an adaptation of the combined DEX/CRH test, and treatment with an antagonist against the vasopressin receptor 1 normalized the HPA axis hyperactivity in these animals." (PMID 22132117, 2011). "Future studies could employ the Hamilton Anxiety Scale or the Spielberger's State-Trait-Anxiety Inventory, as well as measure serum levels of cortisol, adrenocorticotropic hormone (ACTH) and CRH." (PMID 20731814, 2010). "CRH neurons serve as the driving force behind the hypothalamic–pituitary–adrenal (HPA) axis stress response, playing a crucial role in the stress hypothesis of anxiety and depression." (PMID 39859152, 2025). "Apart from the absence of evidence of anxious behavior following the LH episodes in PSH rats, the lack of anxiety was also reflected in a decrease in the initially increased CRH levels in the hypothalamus, bringing them down to the levels observed in the intact control rats." (PMID 38892090, 2024). "Several studies pointed out that anxiety and depression increase the responses to social stress, further stimulating the hypothalamic-pituitary-adrenal (HPA) axis, leading to a higher level of corticotropin-releasing hormone (CRH) and a rise glucocorticoid concentrations." (PMID 37507684, 2023). "Moreover, a negative correlation of anxiety level with ovBNST CRH/-FOSB cell count (ρ=-0.54; p<0.001) and with CRH/CeA SSD (ρ=-0.58; p<0.001) was detected." (PMID 36213293, 2022). "Different species of GABACeA neurons, including those expressing adrenocorticotropin-releasing hormone (CRH), protein kinase C delta (PKCδ), somatostatin (SOM), and neurohypophysin, may have different roles in pain and anxiety regulation." (PMID 36710934, 2022). "However, GHR ablation in CRH neurons caused no significant alterations in metabolism, HPA axis, acute stress response or anxiety in mice." (PMID 34576072, 2021). "Thus, CRH neurons in the nucleusoval of the BNST and serotonergic neurons in DRD appear tohave reciprocal connections that play a role in the control ofemotional behavior, including defensive behavioral responsessimilar to anxiety." (PMID 34901719, 2021). "Subsequently, CRH-specific GHR knockout (KO) mice were generated and possible alterations in metabolism, ghrelin-induced food intake, basal and stress-induced corticosterone secretion, stress-induced activation of PVH neurons and anxiety were determined in male and female mice." (PMID 34576072, 2021). "Consequently, levels of CRH, POMC, ACTH, and cortisol could be treated as biomarkers with potential translational use in depression and anxiety." (PMID 34440536, 2021). "CRH released by extrahypothalamic brain structures directly contributes to behavioral anxiety, regardless of its effecton the pituitary gland and the sympathetic system, since ananxiety-like effect after intraventricular CRH administrationpersists in hypophysectomized rats." (PMID 34901719, 2021). "More recently, in vivo studies with lorazepam and clonazepam demonstrated that both BZDs were effective to reversing anxiety-like behavior, including social-avoidance, and these effects were correlated with their inhibitory effect on the HPA axis, mediated by suppression of CRH activity." (PMID 32499732, 2020).